POC1A (POC1 centriolar protein A)
Diseases named in the same sentence as POC1A in open-access papers (continued):
Sharing a sentence is not in itself a finding about the gene and the disease.
tumor (5 papers, 2019 to 2025). "Furthermore, we investigated the correlation between POC1A expression and immune infiltration, tumour mutation burden (TMB), immune checkpoint expression and drug sensitivity." (PMID 38429900, 2024). "This study thoroughly examined POC1A expression and its implications for diagnosis, staging, prognosis, immune infiltration, tumour mutation burden (TMB), immune checkpoint profiles and drug sensitivity in order to elucidate the clinical significance of POC1A for LUAD." (PMID 38429900, 2024). "Subsequently, we examined the association between POC1A and several anti‐tumour medications, encompassing bortezomib, cisplatin, docetaxel, entinostat, erlotinib, gefitinib, obatoclax mesylate, paclitaxel, savolitinib, temozolomide, vincristine and vinorelbine." (PMID 38429900, 2024). "Therefore, the present study systematically analyzed the relation of POC1A expression with prognosis, tumor mutation burden (TMB), tumor immunity microenvironment, immune checkpoint gene, microsatellite instability (MSI) and drug sensitivity in 33 different tumors using the TCGA database." (PMID 35748773, 2022). "To examine the role of POC1A on tumor growth in vivo, we introduced Poc1a shRNA or Scramble shRNA into 4T1 cells." (PMID 40830747, 2025). "POC1A potentially contributes to tumour development by influencing the cell cycle and immune cell infiltration." (PMID 38429900, 2024). "POC1A exhibited overexpression in most tumour tissues, and its overexpression in LUAD was significantly correlated with late‐stage presentation and poor prognosis." (PMID 38429900, 2024). "It was also found that the expression of POC1A elevated with the increase of tumor stage in nine tumor types." (PMID 35748773, 2022). "The findings revealed that POC1A was shown to be negatively correlated with StromalScore and ImmuneScore in most tumors and positively correlated with tumor purity." (PMID 35748773, 2022). "The relation between POC1A and immunological checkpoints genes, microsatellite instability (MSI) as well as tumor mutation burden (TMB) was also evaluated." (PMID 35748773, 2022). "The StromalScore, ImmuneScore, and ESTIMATEScore of the tumor tissue were calculated using the R language “estimate” package, and their correlation with POC1A expression was evaluated." (PMID 35748773, 2022). "Collectively, these findings imply that elevated POC1A expression is related to immunosuppressive tumor microenvironment." (PMID 35748773, 2022). "It was noticed that POC1A expression was negatively correlated with ImmuneScore and StromalScore while positively correlated with tumor purity in majority of tumors." (PMID 35748773, 2022). "POC1A expression was inversely correlated with tumor size (p=0.043) and lymph node metastasis (p=0.001) in GC patients." (PMID 33052878, 2020). "In summary, we discovered POC1A as a tumor suppressor and found its potential role in affecting the prognosis of GC." (PMID 33052878, 2020). "In particular, our data highlighted MTFR2, MND1, FAM72D, and POC1A as genes whose expression correlates with worse OS prognosis, suggesting their possible involvement in tumor progression and invasion." (PMID 31067633, 2019). "Our findings suggest that POC1A may contribute to tumour development by modulating the cell cycle and immune cell infiltration." (PMID 38429900, 2024). "Similarly, immunohistochemical staining illustrated a more pronounced POC1A expression in tumour tissue compared to para‐carcinoma lung tissue." (PMID 38429900, 2024). "Additionally, Tumor immune infiltration and tumors microenvironment were correlated with the expression of POC1A." (PMID 35748773, 2022). "Importantly, immunosuppressive tumor microenvironment and immune checkpoint genes were noticed to be related to elevated POC1A expression." (PMID 35748773, 2022).
tumor (continued). "Taken together, these findings imply that the POC1A gene might have immunomodulatory functions and that tumor patients with elevated POC1A expression might be in an immunosuppressive condition." (PMID 35748773, 2022). "In addition, analysis of GO enrichment demonstrated that these genes primarily induce cell growth and regulate of cell growth, which corresponded to the result that POC1A expression was correlated with tumor size." (PMID 33052878, 2020). "The GO and KEGG analyses of these genes suggested that POC1A deletion may induce cell growth, which is consistent with our results that POC1A expression is significantly correlated with tumor size." (PMID 33052878, 2020). "However, analysis of coexpressed genes cannot explain the impact of POC1A on tumor volume and lymphocyte metastasis." (PMID 33052878, 2020). "Furthermore, by RT-qPCR and immunohistochemistry staining, we discovered that POC1A, which is highly expressed in adjacent tissues of GC, acted as a tumor suppressor in GC." (PMID 33052878, 2020). "In addition, we also found that POC1A expression was significantly correlated with tumor size and lymphatic metastasis in 3 cohorts." (PMID 33052878, 2020). "Thus, all survival analyses indicated that POC1A acts as a tumor suppressor in GC." (PMID 33052878, 2020). "Our study identified an increase in the expression of POC1A in TNBC tissues, which was found to correlate with tumor size and lymph node metastasis." (PMID 40830747, 2025). "Each tumor sample’s TMB was calculated, and correlation was assessed between POC1A expression and TMB." (PMID 35748773, 2022). "The GSE54129 GC dataset and LASSO regression model (tumor vs. normal) were employed, and 6 significant differentially expressed genes (LAMP5, CEBPB, ARMC9, PAOX, VMP1, POC1A) were identified." (PMID 33052878, 2020). "Furthermore, ESTIMATE analysis unveiled that LUAD samples exhibiting high expression of POC1A showcased lower ESTIMATE, immune and stromal scores, although higher tumour purity." (PMID 38429900, 2024). "Additionally, the high POC1A expression group displayed lower ESTIMATE, immune, and stromal scores, but higher tumour purity." (PMID 38429900, 2024). "Secondly, the direct mechanism of POC1A in tumour immunity has not been conclusively confirmed, and its relationship with drug sensitivity remains a theoretical prediction which may necessitate validation through animal experiments and clinical trials." (PMID 38429900, 2024).
genetic diseases (1 paper, 2020). "Therefore, as the majority of studies of POC1A reported its gene alteration could lead to genetic disease, we verified the positive relationship between POC1A CNA and POC1A expression and investigated changes in gene expression that occurred with POC1A CNA in STAD." (PMID 33052878, 2020).
skeletal dysplasia (1 paper, 2015). Any Mendelian diseases that affects growth and development of the skeleton. "Mice homozygous for the ES-derived null allele of Poc1a have the same growth defect, skeletal dysplasia, and testicular features as Poc1acha/cha mice." (PMID 26496357, 2015).
POC1A also shares sentences with these, for which no sentence is quoted: onychodysplasia (3 papers); acanthosis nigricans (1); cervical carcinoma (1); cholangiocarcinoma (1); chronic myelogenous leukemia (1); Dwarfism (1); dyslipidemia (1); hypertriglyceridemia (1); Kidney Cyst (1); lipodystrophy (1); lung adenocarcinoma (1); microcephaly (1); prostate carcinoma (1); seminoma (1); skin melanoma (1).